ENSG00000212175
Synonyms: LOC124900537
Gene: Small nucleolar RNA gene on chromosome 2 (55,565,703 to 55,565,850, forward strand). Ensembl gene ENSG00000212175.
Gene Ontology:
Biological process: RNA processing
Cellular component: nucleolus
Homologues: Paralogues in human: SNORA12 (86% identical).